TNFRSF1B (TNF receptor superfamily member 1B)
Diseases named in the same sentence as TNFRSF1B in open-access papers (continued):
Sharing a sentence is not in itself a finding about the gene and the disease.
tumor (continued). "TNF-α is a cytokine that binds to TNFRSF1A/TNFR1 and TNFRSF1B/TNFBR, is secreted by macrophages and induces tumor cell death and other inflammatory mediators and proteases that orchestrate inflammatory responses." (PMID 35453307, 2022). "Further in-depth study of each signaling pathway verified that monocytes were directly associated with tumor cells only in the MIF and TNF pathways, in which the most important ligand-receptors were CD74/CD44 and TNF/TNFRSF1B." (PMID 36479092, 2022). "(2022) identified a distinct Treg phenotype that is increased in tumor tissue compared to patient-matched blood and defined by enriched expression of the TNF receptor superfamily member 1B (TNFR2)." (PMID 35757757, 2022). "Tnfrsf1b, equivalent to TNFR2, a gene in the Cytokine- Cytokine receptor interaction signaling pathway, had a significant positive correlation with the areas of tumor metastasis." (PMID 36118769, 2022). "In our dataset, TME-derived TNF appears to interact with HCC tumor cells expressing TNFRSF1B to induce upregulation of HCC-derived CCN2 (log2 fold change = −4.10), MIP2 (log2 fold change = −6.14), and VCAM1 (log2 fold change = −2.46)." (PMID 33995488, 2021). "Missense variants in four genes, EXOG, RANBP2, RANBP6 and TNFRSF1B, were identified in areas of LOH seen in the tumour from P1." (PMID 32357859, 2020). "The core dynamic DEGs (Mnda, Cyp1b1, Comp, Phex, Mmp3, Tnfrsf1b, Fbln5, and Nfkb2) had been reported to be closely related to the development and metastasis in tumor and cancer progress." (PMID 33042984, 2020). "TNFRSF1B is highly expressed not only in tumor cells but also in immunosuppressive cells, including MDSC and Treg cells." (PMID 32039005, 2019). "TNFRSF1B is mainly expressed on malignant cells and in the immunosuppressive cell compartment within the tumor microenvironment." (PMID 32039005, 2019). "In the tumor microenvironment, TNFRSF1B is widely expressed in many types of cells, including immune cells and malignant cells." (PMID 32039005, 2019). "TNFRSF1B promotes tumor progression by maintaining a pro-tumor immune-microenvironment or by promoting the proliferation and survival of malignant cells." (PMID 32039005, 2019). "In SS alterations by point mutations or gain mutations suggest a potential role of oncogenic TNFR2 signaling and increased TNFRSF1B transcript mRNA with expanded expression onto the tumor cell themselves." (PMID 30356161, 2019). "These TNFRSF1B+ Treg cells were earlier found as potent suppressive immune cell subset with enhanced migratory ability that promote disease progression and hamper tumor therapy." (PMID 32039005, 2019). "Tumor cells with high expression of TNFRSF1B resist TNF-induced cell death by ligand binding to TNFRSF1B." (PMID 32039005, 2019). "Similar to tumor cells, TNFRSF1B protects immunosuppressive regulatory T (Treg) cells and myeloid-derived suppressor cells (MDSC) from the death-inducing TNF and thus enhances the proliferation and function of those tumor-promoting cells." (PMID 32039005, 2019). "The interaction of tumor necrosis factor-α (TNF-α) with its receptors: TNFRSF1A and TNFRSF1B is critical for the promotion of tumor growth, invasion and metastasis." (PMID 25010932, 2014). "We further evaluated cumulative survival in subgroups by TNFRSF1B +676 T>G (rs1061622) genotypes and selected factors including age, ethnicity, tumor stage and node status." (PMID 21995493, 2011). "It is possible that this SNP affects the function of TNFRSF1B and enhances radiotherapy or chemotherapy efficacy through inhibiting tumor therapy resistance." (PMID 21995493, 2011). "Furthermore, a tumour‐bearing mice model was constructed to investigate the effects of TNFRSF1B treatment on tumour growth in vivo." (PMID 37712139, 2023). "In addition, the blockade of TNFRSF1B inhibits tumour growth via profoundly remodeling the immune microenvironment in the OC mouse model." (PMID 37712139, 2023).
tumor (continued). "On the other hand, HPV+ tumor cells upregulated the favourable gene TNFRSF1B derived pathway." (PMID 35769468, 2022). "Infliximab and adalimumab, two immune checkpoint inhibitors that could blockade TNF, TNFRSF1A, and TNFRSF1B, were also included in the network, further highlighting the potential utilities in tumor immunotherapy of TNBC." (PMID 36291687, 2022). "It is upregulated in the TME and may induce NF-κB signaling via binding to one of the HCC tumor expressed receptors, such as TNFRSF1B (log2 fold change = −2.24)." (PMID 33995488, 2021). "Four genes (EXOG, RANBP2, RANBP6 and TNFRSF1B) harboured missense variants that fell in a region of LOH in the tumour from the father only, but none showed somatic loss of the wild type allele in the tumour." (PMID 32357859, 2020). "TNF receptor 2 (TNFR2) is a master switch of cell survival and proliferation and antagonist antibodies targeting TNF receptor 2 (TNFR2, TNFRSF1b) can successfully downregulate immunosuppressive T regulatory cells and eliminate tumor cells that overexpress the TNFR2 oncogene for survival." (PMID 32245106, 2020). "Several studies targeting TNFRSF1B already proved its great potential in tumor treating." (PMID 32039005, 2019). "Furthermore, we also found that cumulative survival was different in subgroups by TNFRSF1B +676 T>G (rs1061622) genotypes and selected factors including age, ethnicity, tumor stage and node status." (PMID 21995493, 2011). "Furthermore, we confirmed that high TNFRSF1B expression in primary CD8+T cells resulted in reduced IFN‐γ production, which is necessary for tumour‐killing activity in T cells, determine the mechanistic factors leading to the pro‐tumorigenic effects of TNFRSF1B." (PMID 37712139, 2023). "Blocking TNFRSF1B could directly inhibit tumour growth by suppressing Treg function." (PMID 37712139, 2023). "Additionally, it was reported that TNFRSF1B antibody could elicit anti‐tumour activity and improve the effect of PD‐1 in syngeneic mice tumour models." (PMID 37712139, 2023). "Therefore, TNFRSF1B is closely related to the immunosuppression ability of tumor promoting cells." (PMID 32039005, 2019). "Therefore, TNFRSF1B represents an attractive target for tumor therapy." (PMID 32039005, 2019). "TNFRSF1B (also known as TNFR2), a receptor for the pro-inflammatory cytokine TNF-α, is primarily expressed in immune cells, endothelial cells, and certain tumor cells, playing a pivotal role in immune regulation, inflammation, and cell survival." (PMID 40547917, 2025). "Most notably, among the receptors, the aberrant expression of tumor necrosis factor (TNF) receptor 2 (TNFR2, TNFRSF1B) on the TME cells activates several signaling pathways after the interaction with its ligand, TNF, that support the tumor growth." (PMID 39609700, 2024). "TNFRSF1B, a member of the TNF receptor superfamily highly expressed in Tregs, possesses specificity and serves as a potential driver of immune evasion and tumor proliferation." (PMID 39232806, 2024). "To determine the potential role of infiltrated CD3+CD8+TNFRSF1B+T cells in clinical progression, we immunostained tumour sections from 140 OC patients with 9 years follow‐up to detect CD3, CD8, TNFRSF1B, PD‐1, and IFN‐γ expression." (PMID 37712139, 2023). "TNFRSF1B belongs to TNF receptor (TNFR) superfamilies and plays an important role in protective immunity, inflammatory and tumor immunology." (PMID 35123499, 2022). "FASLG, TNFRSF1B, GATA3, TARDBP, ZBP1, TNFRSF21, and TLR3 are mainly expressed in multiple immune cell types, and immune cells have a role in TME to inhibit tumor progression." (PMID 35899194, 2022). "The qRT-PCR results revealed that AXL (p = 0.0308), FAS (p = 0.0134), TNFRSF1B (p = 0.0250), and CDKN2A (p = 0.0224) mRNA expression were considerably greater in tumor tissues." (PMID 36186479, 2022).
tumor (continued). "Ligand TNF and its receptor TNFRSF1B were found to act as major signaling from CD4+ T cells to CD8+ T2/T3 cells, and the ability of the TNF–TNFRSF1B pair to kill tumor cells in vitro has been reported before." (PMID 35812372, 2022). "TNFRSF1B, a receptor of TNF and lymphotoxia-α, can directly promote tumor cell proliferation and activate immunosuppressive cells." (PMID 34880206, 2021). "We identified multiple tumor-immune interactions, for example between CXCR3, CCL5, TNFRSF1B, and VCAM1-expressing malignant T cells and macrophages/fibroblasts positive for CXCL9, CCR1, GRN, and IGTB1, respectively." (PMID 33816243, 2021). "As TNFRSF1B is more highly expressed than TNFR1 in tumors and tumor-related cells, TNF is likely to have a tumor-promoting function instead of an inhibitory impact." (PMID 32039005, 2019). "The significant upregulation of LTA − TNFRSF1B between CD4-C3 and VCAN+ TAMs suggests that VCAN+ TAMs may facilitate tumor immune suppression and proliferation through interactions with Tregs." (PMID 39232806, 2024). "The immune cell infiltration in the TME of the subcutaneous tumour model was analyzed, and we found that TNFRSF1B blockade did not affect the infiltration of CD3+T cells but affected CD8+T cells." (PMID 37712139, 2023). "TNFRSF1B transcription was alleviated obviously in Tregs in both tumor and TDLNs, regardless of lymph nodes with tumor invasion or not." (PMID 35251045, 2022). "TNFRSF1B usually accelerates the malignant transformation and growth of tumor cells, rather than inducing cell death through apoptosis." (PMID 32039005, 2019). "TNF-α and its receptors, TNFRSF1A and TNFRSF1B belong to the TNF-TNFR superfamily, and the interaction of these genes regulates inflammation and increases the invasive activity and metastatic potential of tumor cells." (PMID 25010932, 2014). "Moreover, targeting TNFRSF1B signaling such as through TNF-α inhibitors could offer therapeutic benefits by mitigating inflammation and tumor development." (PMID 40547917, 2025). "In addition, decreased abundance of TNFRSF1B in CD8+ T cells in the tumour and spleen, indicating that anti‐TNFRSF1B antibody treatment could reduce the suppressed CD8+TNFRSF1B+ T cells." (PMID 37712139, 2023). "Tnfrsf1b, one of the receptors of tumor necrosis factor (TNF), had been identified as a survival factor, which could not only maintain cell survival and enhance proliferation but also participate in the adhesion and migration of tumor cells." (PMID 36118769, 2022). "TNFRSF1A and TNFRSF1B, as the TNF receptors, were highly expressed in epithelial-like and mesenchymal-like malignant cells, suggesting that the TNF signaling pathway may promote tumor metastasis by inducing the EMT process of tumor cells." (PMID 36291687, 2022). "Gene profiling of NK from the tumor where antigen-specific CTL were present showed a strong expression of effector (Gzma, Gzmb, Prf1, and 4.1BB), tissue–migratory (Gpr33 and Ccr5), and signaling (Ifngr, Klhdc2, Eif3s6, Map3k6, Tnfrsf1b, Icos, Ly49G, and Nmi) transcripts." (PMID 31456803, 2019). "Further, expression of lymphotoxin-A and tumor necrosis factor superfamily-14 (TNFSF14/LIGHT) by NK and complementary TNFRSF1B and TNFRSF14/HVEM (herpes virus entry mediator) by CTL may serve as a substrate for CTL–NK compartmentalization in tumors or tumor-draining lymph nodes." (PMID 31456803, 2019). "Moreover, the upregulation of TNFRSF1B, TNFRSF8, TNFRSF9, and TNFRSF10 expression, as well as elevated levels of TNF, suggested apoptotic signal transition through the TNF family membrane receptors, which was also detected in tumour cells treated with chemotherapeutic drugs." (PMID 35804353, 2022).
cancer (178 papers, 2009 to 2026). A tumor composed of atypical neoplastic, often pleomorphic cells that invade other tissues. "Genetic polymorphisms of tumor necrosis factor (TNF) -α and its surface receptors, TNFRSF1A and TNFRSF1B have been examined in terms of susceptibility to various cancers." (PMID 20646319, 2010). "More recently, given that cancer progression is preceded by a long period of subclinical inflammation, the genetic polymorphisms of TNF-α, TNFRSF1A and TNFRSF1B have been examined in terms of susceptibility to various cancers." (PMID 20646319, 2010). "As the presence of TNFR2 in the blood and TME has been associated with unfavorable prognosis in several types of cancer, it is possible that the presence of TNFRSF1B rs2275416 may also affect PCa prognosis, given its association with both GS and PSA levels." (PMID 37108754, 2023). "Of a particular significance are two TNF-α SNPs (SNP -308 G>A and -1031 T>C in the promoter region) and one TNFRSF1B SNP (+676 T>G in exon 6), which have been widely investigated for their associations with susceptibility to and progression and prognosis of various cancers." (PMID 21995493, 2011). "Furthermore, functional polymorphisms in TNF-α and TNFRSF1B genes that alter gene expression are likely to be associated with risk and clinical outcomes of cancers." (PMID 21995493, 2011). "For instance, in adults, TNF-α, produced by immune cells such as lymphoid and macrophage populations, can inhibit T-cell response and activation of cancer cytotoxic T-call activation through interactions with its receptor TNFRSF1B (TNFR2)." (PMID 39796780, 2025). "We found that this parameter was affected by IL2RA rs7093069 and TNFRSF1B rs2275416, implying the strong impact of genetic variability within immune genes on cancer development, progression, and staging." (PMID 37108754, 2023). "Although we found that TNFRSF1B knockdown had only a slight impact on proliferation abilities, down-expression of TNFRSF1B dramatically promoted the migration capacity of cancer cells MKN45 and SNU601." (PMID 36671486, 2023). "The TNFRSF1B gene (also known as TNFR2) and its variants have previously been linked with inflammatory responses, inflammatory disease outcomes, and rate of cancer progression, but the role of these gene variants in AD has yet to be elucidated." (PMID 33716716, 2021). "Most of the genes in the subnetworks were inflammatory cytokines and participated in TNF signaling pathways and pathways in cancer, such as Ccl2, Ccl20, Csf1, Cx3cl1, Cxcl1, Cxcl3, Il6, Birc3, Map3k8, Nos2, Nfkb2, Tnfrsf1b, and Vcam1." (PMID 33042984, 2020). "Both the SCP2 and BSG branches share the same CAV1 upstream regulators such as MAPK3, TNFRSF1B, and GNAI2, which have been implicated in cancer cells death pathways." (PMID 24949431, 2014). "Understanding genetic variations in TNFRSF1B may also inform precision medicine approaches that address the dual challenges of cancer and metabolic dysregulation." (PMID 40547917, 2025). "Furthermore, polymorphism of TNFRSF1B, the gene encoding TNFR2, is associated with the risk, survival, or response to the treatment of cancer patient." (PMID 36923938, 2023). "Previous study found that targeting antagonism against Tnfrsf1b might be a potential therapeutic approach for tumors by simultaneously inhibiting Treg activity and inducing cancer cell death." (PMID 36118769, 2022). "Long-term F. nucleatum stimulation may increase the risk of cell carcinogenesis by altering many inflammation- and cancer-related genes and pathways, such as Mnda, Cyp1b1, Comp, Phex, Mmp3, Tnfrsf1b, Fbln5, and Nfkb2." (PMID 33042984, 2020). "All of these characteristics make TNFRSF1B an ideal candidate for targeted cancer therapy." (PMID 32039005, 2019). "Mediating those direct and indirect effects, TNFRSF1B exacerbates cancer progression." (PMID 32039005, 2019).
cancer (continued). "Furthermore, we also were able to identify genes such as BRCA1, ABCA1, TNFRSF1B, MLLT11 that have been associated with various types of cancers." (PMID 22594378, 2012). "The DNA methylation patterns of core CERGs in the 20 cancer types were also observed, and some of these genes, such as IKBKG and TNFRSF1B, showed consistent hypomethylation." (PMID 38297270, 2024). "Additionally, the average expression of TNF-related genes, including TNFRSF1A, TNFRSF1B, TNFSF10, and TNFRSF21, was higher than that of most other necroptosis genes in pan-cancer." (PMID 37000317, 2023). "SLC11A1, TNFRSF1B, and LTBR have not yet been reported on prognostic factors in GBM, thus, suggestive of novel target candidates for cancer immunotherapy." (PMID 29721184, 2018).
infection (75 papers, 2008 to 2026). The state of being infected such as from the introduction of a foreign agent such as serum, vaccine, antigenic substance or organism. "We investigated the impact of infection and parasite opsonization on the TLR/NLRP3-activated, canonical NF-κB pathway, and on the CD40/TNFRSF1b-activated, alternative NF-κB pathway linked to cross-presentation." (PMID 32582184, 2020). "Consistently, VSV titers were reduced in spleen tissue shortly after infection in Tnfrsf1a−/− animals, in sharp contrast to the findings in WT and Tnfrsf1b−/− mice." (PMID 29142134, 2018). "The mRNA expression of IL1R2 and TNFRSF1B was increased by 4- and 2-fold, respectively, in WT mice at day 8 after infection." (PMID 24750819, 2014). "Given that all of Tnfrsf1b’s induced enhancers coincide with a SE, we hypothesise that the activation of the SE upon infection is driving the process in conjunction with increased eRNA expression from the induced enhancers." (PMID 30669987, 2019). "In order to test this hypothesis, we identified network neighbors of Kepi and Tnfrsf1b from the wild type infection studies, as well as genes co-occupying the same WGCNA modules of these genes." (PMID 27663205, 2016). "The genes, Ccl2, Ccl20, Csf1, Cx3cl1, Cxcl1, Cxcl3, Il6, Birc3, Map3k8, Nos2, Nfkb2, Tnfrsf1b, and Vcam1, played core roles in a PPI network, and interacted closely with other ones in the infection." (PMID 33042984, 2020). "Inflammatory response genes, such as NOS2, IL6 and TNFRSF1B, were up-regulated while some positive regulation of inflammatory response genes, such as TLR3, STAT5 and LRRC32, were also elevated post-infection with IBDV." (PMID 28486945, 2017). "The TNFα receptor 2 (Tnfrsf1b) was identified by our analysis as having high degree centrality but we found that infection of Tnfrsf1b−/− mice had only a modest and non-significant effect on the weight loss phenotype (data not shown)." (PMID 27663205, 2016). "In contrast, transcript expression of the TNF-α receptors TNFR1 (Tnfrsf1a) and TNFR2 (Tnfrsf1b) were not altered in the brain following infection, suggesting that enhanced TNF-α signaling in this setting is mediated primarily through induction of cytokine expression." (PMID 35462541, 2022).
kidney diseases (19 papers, 2013 to 2025). "Importantly, this smartphone-based analyzing and reporting system allows for discriminating LN patients with active renal disease from healthy controls with the area-under-the-curve (AUC) value = 0.9 for TNFRSF1b and 1.0 for VSIG4, respectively, indicating high predictive accuracy." (PMID 38534254, 2024). "Eighteen differentially expressed proteins were found to overlap between the CKD and post-transplant CKD groups including biomarkers of kidney disease (cystatin C, β2-microglobulin, and REN) and biomarkers of inflammation (CFD, IGFBP-2, PRSS 2, Chemokine Ligand 15 (CCL-15), and TNFRSF-1B)." (PMID 33888746, 2021).
neurodegenerative disease (16 papers, 2011 to 2025). A disorder of the central nervous system characterized by gradual and progressive loss of neural tissue and neurologic function. "Hence, Tnfrsf1b is determined to be a potential therapeutic target to treat inflammatory and neurodegenerative diseases." (PMID 40869347, 2025).
cardiovascular disease (10 papers, 2011 to 2025). "Third, TNFRSF1B has been related to cardiovascular disease and mortality in the Framingham Heart Study." (PMID 37623250, 2023).